SOX9 (SRY-box transcription factor 9)
Description:
Transcription factor that plays a key role in chondrocytes differentiation and skeletal development. Specifically binds the 5'-ACAAAG-3' DNA motif present in enhancers and super-enhancers and promotes expression of genes important for chondrogenesis, including cartilage matrix protein-coding genes COL2A1, COL4A2, COL9A1, COL11A2 and ACAN, SOX5 and SOX6. Also binds to some promoter regions (By similarity). Plays a central role in successive steps of chondrocyte differentiation (By similarity). Absolutely required for precartilaginous condensation, the first step in chondrogenesis during which skeletal progenitors differentiate into prechondrocytes (By similarity). Together with SOX5 and SOX6, required for overt chondrogenesis when condensed prechondrocytes differentiate into early stage chondrocytes, the second step in chondrogenesis (By similarity). Later, required to direct hypertrophic maturation and block osteoblast differentiation of growth plate chondrocytes: maintains chondrocyte columnar proliferation, delays prehypertrophy and then prevents osteoblastic differentiation of chondrocytes by lowering beta-catenin (CTNNB1) signaling and RUNX2 expression (By similarity). Also required for chondrocyte hypertrophy, both indirectly, by keeping the lineage fate of chondrocytes, and directly, by remaining present in upper hypertrophic cells and transactivating COL10A1 along with MEF2C (By similarity). Low lipid levels are the main nutritional determinant for chondrogenic commitment of skeletal progenitor cells: when lipids levels are low, FOXO (FOXO1 and FOXO3) transcription factors promote expression of SOX9, which induces chondrogenic commitment and suppresses fatty acid oxidation (By similarity). Mechanistically, helps, but is not required, to remove epigenetic signatures of transcriptional repression and deposit active promoter and enhancer marks at chondrocyte-specific genes (By similarity). Acts in cooperation with the Hedgehog pathway-dependent GLI (GLI1 and GLI3) transcription factors (By similarity). In addition to cartilage development, also acts as a regulator of proliferation and differentiation in epithelial stem/progenitor cells: involved in the lung epithelium during branching morphogenesis, by balancing proliferation and differentiation and regulating the extracellular matrix (By similarity). Controls epithelial branching during kidney development (By similarity).
Synonyms: SRA1; CMD1; CMPD1; ENH13; SRXX2; SRXY10; TESCO
Tractability: PROTAC: UniProt records ubiquitination sites on it; ubiquitination databases record sites on it.
Target class: Transcription factor
Gene: Protein-coding gene on chromosome 17 (72,121,020 to 72,126,416, forward strand). Ensembl gene ENSG00000125398.
Subcellular location: Nucleus
Subcellular location (Human Protein Atlas): Nucleoplasm
Pathways (Reactome):
Developmental Biology: Developmental Lineage of Multipotent Pancreatic Progenitor Cells; Developmental Lineage of Pancreatic Acinar Cells; Developmental Lineage of Pancreatic Ductal Cells; Transcriptional and post-translational regulation of MITF-M expression and activity; Transcriptional regulation of testis differentiation
Gene expression (Transcription): Transcriptional regulation by RUNX2
Signal Transduction: Deactivation of the beta-catenin transactivating complex
Gene Ontology:
Molecular function: chromatin binding; cis-regulatory region sequence-specific DNA binding; DNA-binding transcription activator activity, RNA polymerase II-specific; DNA-binding transcription factor activity; DNA-binding transcription factor activity, RNA polymerase II-specific; protein binding; protein kinase A catalytic subunit binding; RNA polymerase II cis-regulatory region sequence-specific DNA binding; sequence-specific DNA binding; sequence-specific double-stranded DNA binding; beta-catenin binding; bHLH transcription factor binding; DNA binding; pre-mRNA intronic binding; transcription cis-regulatory region binding
Biological process: aortic valve morphogenesis; cellular response to interleukin-1; cellular response to retinoic acid; cellular response to transforming growth factor beta stimulus; chondrocyte differentiation involved in endochondral bone morphogenesis; chromatin remodeling; male gonad development; negative regulation of biomineral tissue development; negative regulation of DNA-templated transcription; negative regulation of miRNA transcription; negative regulation of ossification; negative regulation of transcription by RNA polymerase II; nucleosome assembly; positive regulation of cartilage development; positive regulation of cell population proliferation; positive regulation of chondrocyte differentiation; positive regulation of chondrocyte proliferation; positive regulation of DNA-templated transcription; positive regulation of epithelial cell migration; positive regulation of epithelial cell proliferation; positive regulation of gene expression; positive regulation of male gonad development; positive regulation of mesenchymal stem cell differentiation; positive regulation of transcription by RNA polymerase II; prostate gland development; and 68 more
Cellular component: nucleoplasm; nucleus; protein-containing complex; chromatin; transcription regulator complex
Genetic constraint (gnomAD): Loss-of-function variants: 2 observed, 40.84 expected, observed/expected ratio (o/e) 0.049, 90% interval 0.019 to 0.15. The upper end of that interval is the gene's LOEUF score, 0.15, which puts it in group 1 of 6, group 1 being the genes least tolerant of losing a copy. Missense variants: 583 observed, 703.23 expected, observed/expected ratio (o/e) 0.83, 90% interval 0.77 to 0.89. Synonymous variants: 381 observed, 333.52 expected, observed/expected ratio (o/e) 1.14, 90% interval 1.05 to 1.24.
Gene-disease validity (ClinGen):
ClinGen rates the evidence that SOX9 causes each of these diseases.
campomelic dysplasia (autosomal dominant): Definitive.
Cooks syndrome (autosomal dominant): Limited. Cooks syndrome is a malformation syndrome affecting the apical structures of digits and presenting with hypo/aplasia of nails and distal phalanges.
isolated Pierre-Robin syndrome (autosomal dominant): Limited. Pierre-Robin syndrome (or Pierre-Robin sequence) is characterized by triad of orofacial morphological anomalies consisting of retrognathism, glossoptosis and a posterior median velopalatal cleft.
Homologues: Orthologues: chimpanzee SOX9 (100% identical), macaque SOX9 (99% identical), pig SOX9 (98% identical), mouse Sox9 (97% identical), dog SOX9 (97% identical), rat Sox9 (96% identical), rabbit SOX9 (84% identical), tropical clawed frog sox9 (81% identical), zebrafish sox9a (71% identical), zebrafish sox9b (56% identical), Drosophila melanogaster Sox14 (17% identical), Drosophila melanogaster Sox21a (15% identical), and 2 more. Paralogues in human: SOX10 (52% identical), SOX8 (46% identical), SOX30 (20% identical), CFAP65 (20% identical), SOX17 (20% identical), SOX6 (19% identical), SOX7 (19% identical), SOX18 (18% identical), SOX11 (17% identical), SOX5 (17% identical), SOX4 (17% identical), SOX2 (17% identical), and 8 more.
Diseases named in the same sentence as SOX9 in open-access papers:
SOX9 is named in the same sentence as 466 diseases in open-access papers, as found by Europe PMC text mining. Sharing a sentence is not in itself a finding about the gene and the disease. The quoted sentences say what the papers report.
breast carcinoma (148 papers, 2008 to 2026). "In breast cancer, SOX9 expression has been linked to regulation of cancer stem cell properties, EMT, metastasis and poor clinical prognostic." (PMID 38275880, 2024). "ROCR has been implicated in promoting breast cancer proliferation by facilitating the expression of the oncogenic transcription factor SOX9." (PMID 38408075, 2024). "Nevertheless, we appreciate this pioneering study reporting that higher SOX9 mRNA expression in breast cancer was associated with worse prognosis." (PMID 37179317, 2023). "Together, these studies suggest that the loss of SLK results in the activation of Sox9 that can directly induce Sox10 expression in murine tumors as well as human breast cancers." (PMID 33985544, 2021). "Many basic and clinical studies have associated SOX9 overexpression with tumor malignancy and tumorigenesis in lung, colorectal, prostate and breast cancer." (PMID 31060551, 2019). "It will be necessary to undertake further work in order to decipher the molecular mechanisms underlying the deregulated expression of the SOX9 gene in breast cancer." (PMID 26930713, 2016). "SOX9 promotes the mammary stem cell state, is associated with poor prognosis in breast cancer, and is thought to be especially active in triple negative tumors, where it enhances the tumorigenic phenotype." (PMID 27880766, 2016). "The co-expression of exogenous SOX9 and Slug transforms differentiated luminal cells into mammary stem cells (MaSCs), promotes the tumorigenic and metastasis-seeding abilities of human breast cancer cells, and is associated with poor patient survival." (PMID 26009899, 2015). "In another study, expression of miR-140, which targeted Sox9 directly, was seen to be lower in breast cancer patients and cancer stem cells and was associated with increased SOX9 expression." (PMID 25527186, 2014). "Protein overexpression of Slug, Sox9 and Sox10 were associated with poor overall survival and with triple-negative phenotype in breast cancer." (PMID 24404438, 2013). "In breast cancer an increase of SOX9 was associated with an endocrine therapy failure." (PMID 39180200, 2025). "Additionally, high expression of SOX9 is associated with a poorer prognosis for patients with breast cancer." (PMID 38254873, 2024). "Furthermore, cytoplasmic SOX9 protein showed a direct contribution to poor clinical outcomes associated with breast cancer invasiveness, whereas nuclear SOX9 protein expression was more common in the early stages of differentiation of breast cancer cells." (PMID 35159173, 2022). "Moreover, it has been shown that high levels of SOX9 are associated with shorter survival and poor clinical outcome in breast cancer patients." (PMID 34768751, 2021). "PML is upregulated in metastatic breast cancer and non-metastatic breast cancer with a poor prognosis, and studies indicate that PML may be involved in expression of the stem cell factor SOX9 and associated initiation of breast cancer." (PMID 33324553, 2020). "Moreover, co-expression of exogenous Slug and Sox9 increased the tumorigenic and metastatic abilities of breast cancer cells and was associated with poor outcomes in breast cancer patients." (PMID 32398735, 2020). "Furthermore, co-expression of SOX9 and Slug promotes the tumorigenic and metastasis-seeding capacities of breast cancer cells and is associated with unfavorable survival." (PMID 30658681, 2019). "In the mouse, Sox9 has been shown to be a key re-gulator of mammary gland development and stem/progenitor cell maintenance and, in breast cancer patients, high-Sox9 expression has been associated with estrogen receptor (ER)-negative tumours, significantly shorter overall survival and poor survival." (PMID 30622340, 2019). "Furthermore, coexpression of Sox9 and Slug, which is an important player in epithelial-to-mesenchymal transition, promotes the tumorigenic and metastasis-seeding abilities of human breast cancer cells and is associated with poor patient survival." (PMID 29970901, 2018).
breast carcinoma (continued). "Sox9, Sox10 and Slug were shown to be associated with poor overall survival in breast cancer." (PMID 24404438, 2013). "Interestingly, hypermethylation has be implicated in the downregulation of CLDN7 expression in breast cancer and two transcription factors, Tcf-4 and Sox9, have been shown to cooperate in CLDN7 repression in colon cells." (PMID 21789222, 2011). "SRY-Box Transcription Factor 9 (SOX9), a known regulator of mammary stem and progenitor cells, also promotes resistance to therapy and metastasis in breast cancers." (PMID 42239249, 2026). "In breast cancer datasets, we observe elevated expression of SOX9 and SEMA7A in triple-negative breast cancers, as well as in the mesenchymal subtype of triple-negative breast cancers, suggesting disruption of this regulatory axis in breast cancer." (PMID 42239249, 2026). "Studies have demonstrated that downregulation of miR-134-3p and miR-224-3p increases SOX9 levels, thereby promoting breast cancer progression." (PMID 41230330, 2025). "The transcription factor SOX9, markedly upregulated in breast cancer patient samples, serves as a key regulator of breast cancer cell survival and metastasis." (PMID 41230330, 2025). "Studies in breast cancer and non‐small cell lung carcinoma have also pointed out that SOX9 contributes to tumor progression and a poor prognosis for patients." (PMID 39180200, 2025). "Clinical relevance was determined by quantifying serum miR-145-5p and SOX9 mRNA in healthy controls and breast cancer patients before and after DOX treatment." (PMID 41225749, 2025). "Our study uncovers that HuR targets SOX9 mRNA in breast cancer cells and provides compelling evidence supporting HuR’s involvement in cell migration and invasion." (PMID 38254873, 2024). "By ranking them by their activity, we found that SOX9 was among the most enriched TFs in the metastatic tumoroids and was expressed in breast cancer." (PMID 38503727, 2024). "The silencing of HuR in breast cancer cells produces a phenotype that mimics that produced by the silencing of SOX9." (PMID 38254873, 2024). "SOX9 cooperates with the transcription factor Slug to determine mammary stem cell (MaSC) status, and coexpression of both Slug and SOX9 promotes the development of breast cancer, as well as the ability for metastasis." (PMID 38725852, 2024). "This blockade of TF signaling resulted in decreased levels of epithelial-to-mesenchymal transition, reduced cancer stemness, and a decrease in the expression of pro-metastatic markers, namely Slug and SOX9, across multiple breast cancer cell lines." (PMID 39075362, 2024). "In breast cancer, SOX9 is involved in promoting EMT, metastasis, survival, drug resistance, stem cell maintenance, immune evasion, and modulation of the tumor microenvironment." (PMID 38254873, 2024). "In breast cancer, the SOX9 3′UTR is targeted by different miRNAs (miR-133b, -134, -140, -190, 215, and -224), leading to reduced SOX9 expression and operating as tumor suppressors, reducing the metastasis of breast cancer cells." (PMID 38254873, 2024). "By upregulating HDAC5, c-MYC promotes the deacetylation of SOX9, which subsequently leads to its nuclear translocation, contributing to tamoxifen resistance in breast cancer." (PMID 38331879, 2024). "In summary, our data uncovered a new functional relationship between HuR and SOX9 in breast cancer cells." (PMID 38254873, 2024). "To further confirm the role of BCA2 in promoting breast cancer stemness through SOX9, we generated HCC1806 and HCC1937 cells with BCA2 knockout and subsequently overexpressed SOX9." (PMID 38725852, 2024).
breast carcinoma (continued). "Taken together, BCA2 promotes breast cancer stemness by activating LPS-mediated NF-κB signaling and upregulating the expression of SOX9." (PMID 38725852, 2024). "After ATP treatment of breast cancer cells, the expression of Y-box 9 (SOX9) in sex determination area was up-regulated." (PMID 39738256, 2024). "Especially in breast cancer, SOX9 was identified as an important driver of cancer progression and has thus been referred to as “master regulator” of breast cancer cell fate." (PMID 35779228, 2023). "SOX9 is expressed in a variety of cancers, including pancreatic cancer, breast cancer, and prostate cancer." (PMID 37328795, 2023). "Screening for miRNAs with known inhibitory effect on breast cancer cell proliferation and a seed sequence specific for the 3′-UTR of the SOX9 encoding mRNA, we determined miR-224-3p which had been published to inhibit proliferation of MDA-MB-231 cells." (PMID 35779228, 2023). "Here, we investigated the miRNA-mediated regulation of SOX9 expression in two breast cancer cell lines, thereby providing further insights into cellular mechanisms driving breast cancer progression." (PMID 35779228, 2023). "SOX9 was researched more frequently in other solid tumors like colon cancer, hepatocellular carcinoma, and breast cancer." (PMID 37384286, 2023). "We demonstrate that miR-134-3p, miR-224-3p, and miR-6859-3p diminish SOX9 expression in human breast cancer cells." (PMID 35779228, 2023). "miR-134-3p and miR-224-3p function through direct interaction with the SOX9 3′-UTR in breast cancer cell lines." (PMID 35779228, 2023). "SLUG (or SNAI2) and SOX9 are two key TFs that regulate stemness in mammary cells, and they promote the tumorigenic and metastasis-seeding abilities of human breast cancer cells." (PMID 37117180, 2023). "Of note, there has been accumulating evidence of the relevance of SOX9 for breast cancer biology and its role as a “master regulator” of TNBCs." (PMID 37179317, 2023). "HDAC5-mediated SOX9 deacetylation induces SOX9 nuclear localization in HR-positive breast cancer, and HDAC5 overexpression promotes cell growth under tamoxifen exposure." (PMID 37568822, 2023). "In this study we investigated how miRNAs can inhibit expression of the transcription factor SOX9, representing the “master regulator” of cell fate in breast cancer cells." (PMID 35779228, 2023). "The two areas were split by the enrichment of cancer stem cells (CSCs), which, in breast cancer, we mark with the Sox9 marker." (PMID 36672243, 2023). "Conversely, in breast cancers with low SOX9 expression, a SOX9-mediated suppressive effect on death-inducing gene expression cannot be exerted, resulting in reduced cell growth, decreased cell survival, EMT, and metastasis." (PMID 35159173, 2022). "For example, the majority of basal-like tumors are derived from luminal progenitors where SOX9 drives luminal to basal plasticity during basal-like breast cancer development." (PMID 36171192, 2022). "These analyses together point to a transcriptional association between Sox9 levels and genes upregulated with LATS1/2 deletion in human basal-like breast cancers." (PMID 36443313, 2022). "We also performed a similar analysis comparing Sox9 gene expression levels with the activity of genes upregulated by LATS1/2 deletion in human breast cancers, finding a strong correlation in the basal-like subtype." (PMID 36443313, 2022). "Prior to IFNγ stimulation, the TFs demonstrating the highest connectivity were dominated by TFs previously identified for regulating facets of breast cancer biology (in black), including SOX9, GATA3, and ETV6." (PMID 35902886, 2022). "Lineage plasticity is important for the development of aggressive BLBC, transcription factor SOX9 can regulate cell phenotypic plasticity and breast cancer progression." (PMID 36046046, 2022).